FNDC5 (fibronectin type III domain containing 5)
Diseases named in the same sentence as FNDC5 in open-access papers (continued):
Sharing a sentence is not in itself a finding about the gene and the disease.
heart failure (9 papers, 2013 to 2025). Inability of the heart to pump blood at an adequate rate to meet tissue metabolic requirements. "In addition, FNDC5 expression in the skeletal muscle is also correlated with the aerobic performance of heart failure patients." (PMID 36135450, 2022). "The data suggest that FNDC5 may be considered as a promising biomarker and therapeutic target for heart failure." (PMID 36135450, 2022). "High aerobic cardiopulmonary exercise can improve FNDC5 expression in patients with heart failure." (PMID 34440871, 2021). "During heart failure (HF), the expression FNDC5 was related to an improvement in the aerobic performance in HF patients, therefore suggesting that FNDC5 may work as a hormone counteracting stress coming from injury, tissue damage, hypoxia, and inflammation." (PMID 28373915, 2017). "In this sense the FNDC5 expression in a skeletal muscle biopsy from heart failure (HF) patients, it was observed that this expression relates to functional capacity in a human HF and that a decrease in FNDC5 expression might reduce aerobic performance in HF patients." (PMID 24298283, 2013). "The first study in patients with heart failure revealed high PGC-1α and FNDC5 expression from skeletal muscle biopsy samples correlation with a better functional capacity." (PMID 34440871, 2021). "Previously we reported that 5 weeks of exercise training also did not affect FNDC5 expression in the LV of rats with heart failure post‐MI." (PMID 31883222, 2019).
Hepatic steatosis (9 papers, 2019 to 2025). Steatosis is a term used to denote lipid accumulation within hepatocytes. "Two independent groups showed that the rs3480 polymorphism in Fndc5 3' untranslated region was associated with hepatic steatosis and fibrogenesis in human NAFLD patients 64,65." (PMID 33754067, 2021). "Among them, Fndc5/Irisin, which is well known to promote the browning of white adipose tissue, enhances muscle hypertrophy and alleviates obesity and hepatic steatosis, was significantly decreased in both NAFLD and NASH groups." (PMID 35265044, 2022). "For example, liraglutide (LRG) and Fibronectin type III domain-containing 5 (FNDC5) protein can improve hepatic steatosis and reduces hepatic lipid accumulation by inducing autophagy." (PMID 31835352, 2019).
sarcopenia (9 papers, 2021 to 2026). Progressive decline in muscle mass due to aging which results in decreased functional capacity of muscles. "BACKGROUND: Irisin which is encoded by FNDC5 gene, has emerged as a promising therapeutic candidate for alleviating sarcopenia; however, its long-term therapeutic application in muscle regeneration remains insufficiently developed." (PMID 41840428, 2026). "The influence of Fndc5/irisin deficiency on sarcopenia in 22-month-old Fndc5/irisin knockout mice was evaluated." (PMID 38672282, 2024). "In human muscle, irisin, IGF-1, FNDC5 (which encodes the irisin precursor) increase after exercise, and irisin is independently associated with sarcopenia." (PMID 35250869, 2022). "Furthermore, two polymorphisms within the FNDC5 promoter (rs16835198 and rs726344) are both known to impact insulin sensitivity, and insulin sensitivity is a contributing factor for developing sarcopenia." (PMID 38790190, 2024). "Knockdown of igdb‐1/FNDC5 extended worm lifespan and healthspan, countering human studies implicating low circulating FNDC5 as a sarcopenia biomarker." (PMID 37722921, 2023). "Because C. elegans lack an endoskeleton, these findings espouse agxt‐2/BAIBA and igdb‐1/FNDC5 as muscle‐intrinsic, bone‐independent mechanisms of bisphosphonate action on improving sarcopenia." (PMID 37722921, 2023). "This FNDC5-ITGAVB5-FAK-mTOR-Bgn-TLR4 signaling axis was also validated in a sarcopenia mouse model." (PMID 41840428, 2026). "From a clinical perspective, genes such as RBP4 and FNDC5 could serve as promising biomarkers for the early detection and monitoring of metabolic–muscular dysfunction in both sarcopenia and T2DM." (PMID 40869253, 2025). "Another study reported a protective effect of the gene variant on advanced liver fibrosis, but the prevalence of sarcopenia and liver histologic features is not different across the different genotypes of FNDC5 polymorphism." (PMID 34858322, 2021). "In contrast, newer myokines/adipokines FNDC5, METRNL, RETN, and NAMPT, together with AdipoQ in sarcopenia, were uniformly negatively correlated, suggesting a counter-regulatory or compensatory circuit activated by mitochondrial stress." (PMID 40869253, 2025). "Furthermore, in sarcopenia mouse models, AAV-mediated FNDC5 supplementation activated integrin αVβ5-related signaling as expected, resulting in increased muscle mass and alleviation of sarcopenia symptoms." (PMID 41840428, 2026). "Our data indicates that dysfunction of the PGC-1α, FNDC5, and TGF-β collagen axis might result in sarcopenia in patients with CKD." (PMID 37878003, 2023).
Hyperglycemia (8 papers, 2017 to 2024). An increased concentration of glucose in the blood. "On the other hand, several characteristics of T2D, such as hyperglycemia, hypertriglyceridemia, visceral adiposity, and extramyocellular lipid deposition, were negatively associated with adipose tissue FNDC5 mRNA and circulating irisin." (PMID 36614864, 2022). "In animal models, it has also been proven that the overexpression of FNDC5 increases the serum levels of irisin and improves hyperglycemia and hyperinsulinemia, leading in an improvement in the insulin resistance of the mice." (PMID 37448465, 2023). "In an obese mouse model, overexpression of FNDC5 enhances energy expenditure, lipolysis, and insulin sensitivity, and improves hyperlipidemia, hyperglycemia, and hyperinsulinemia." (PMID 36004352, 2022). "Furthermore, the hyperglycemia and hypertriglyceridemia found in our T2DM group might also be negatively associated with adipose tissue FNDC5 mRNA expression and circulating irisin." (PMID 31015797, 2019). "However, the better hypothesis must be the negative influence of hyperglycemia and serum lipids on FNDC5/irisin levels, since free fatty acid and glucose in vitro stimulation decrease expression/secretion of these peptides." (PMID 29412381, 2017).
myocardial infarction (8 papers, 2020 to 2025). Gross necrosis of the myocardium, as a result of interruption of the blood supply to the area, as in coronary thrombosis. "Importantly, FNDC5 / irisin has been found to play a therapeutic role in myocardial infarction and cerebral infarction by regulating the function of BMSCs." (PMID 38500202, 2024). "Moreover, overexpression of FNDC5 could attenuate oxidative damage and cell apoptosis, which have been documented in disease models of vascular aging, myocardial infarction, kidney injury, osteoarthritis and liver ischemia." (PMID 38802337, 2024). "Moreover, aerobic exercise can effectively activate the FNDC5/irisin and PI3K/AKT signaling pathways, promote the polarization of M2 macrophages, and inhibit the inflammatory response of the liver after myocardial infarction." (PMID 38143500, 2023).
osteoporosis (8 papers, 2020 to 2025). A condition of reduced bone mass, with decreased cortical thickness and a decrease in the number and size of the trabeculae of cancellous bone (but normal chemical composition), resulting in increased fracture incidence. "A recent study revealed that the susceptibility of adult female offspring to osteoporosis (OP) induced by PPE is linked to changes in the skeletal muscle mitochondrial autophagy/FNDC5 axis." (PMID 40860437, 2025). "Irisin, a protein encoded by FNDC5 gene, improved symptoms in osteoporosis mice through intraperitoneal injection, while the inhibitor of p38/MAPK pathway weakened this function of irisin." (PMID 38500202, 2024). "Exposure to prednisone during pregnancy reduces FNDC5 expression in fetal skeletal muscle, simultaneously increasing its susceptibility to osteoporosis." (PMID 39337601, 2024). "Therefore, increasing the level of FNDC5/Irisin in vivo can promote the osteogenic differentiation of BMSCs, which is beneficial for patients with osteoporosis." (PMID 38500202, 2024). "Furthermore, we also found that p38/MAPK pathway inhibitor not only weakened the function of FNDC5 to promote osteogenic differentiation in vitro, but also weakened the ameliorating effect of irisin on osteoporosis mice in vivo." (PMID 38500202, 2024). "Therefore, our results indicated that FNDC5 / irisin promoted the osteogenic differentiation of BMSCs by activating the p38/MAPK pathway, thereby improving the symptoms of osteoporosis mice." (PMID 38500202, 2024). "During the growth process of FNDC5-/- mice, bone mass decreased more sharply compared with normal age-matched mice, which accelerated the process of osteoporosis." (PMID 35002510, 2022). "In the absence of estrogen due to OVX, FNDC5-KO mice had increased bone protection from osteoporosis by preventing osteoclast proliferation and eroded surfaces." (PMID 34502045, 2021). "In our study, JGSQP activated the expression of p-AKT along with multiple bone formation and adipogenesis-related genes (Wnt10b, Osx, BMP2, PPARγ, Fabp4, and Fndc5), suggesting that it may ameliorate murine OVX-induced osteoporosis with KYD by controlling the bone-fat balance via the AKT pathway." (PMID 32963560, 2020).
breast carcinoma (7 papers, 2022 to 2025). "Numerous studies have shown that FNDC5 plays an important role in cancer diseases, including many types of malignancies, namely breast cancer, lung cancer, reproductive tract cancer, and bone cancer." (PMID 36386179, 2022). "On the other hand, rs726344, a FNDC5 SNP (single-nucleotide polymorphism), known for altering insulin sensitivity, was significantly associated with weight change at 18 months of breast cancer diagnosis in univariate, but not multivariate, analysis." (PMID 40725790, 2025). "Notably, PGC1-α activates FNDC5 to increase the secretion of Irisin and decorin evokes mitophagy in breast carcinoma cells via PGC-1α and mitostatin." (PMID 35159071, 2022). "In contrast, higher FNDC3A, FNDC4, and FNDC5 predicted better survival for breast cancer patients." (PMID 36626432, 2022). "Additionally, FNDC5 may serve as a prognostic biomarker for basal breast cancer." (PMID 36626432, 2022).
cognitive decline (7 papers, 2022 to 2026). "EE mitigates age-related cognitive decline in association with coordinated neuronal, glial, vascular, and FNDC5/irisin-related signaling changes, supporting BBB/NVU preservation and cognitive resilience during aging." (PMID 41751786, 2026). "In agreement with this, age-associated cognitive decline has been shown to be counteracted by exercise-induced activation of the PGC-1α/FNDC5/irisin signaling pathway." (PMID 37834132, 2023). "Lactate, an exercise-induced myokine, penetrates the blood–brain barrier (BBB) and triggers the BDNF pathway, potentially safeguarding against cognitive decline and neurodegeneration through the SIRT1/PGC1/FNDC5 pathway." (PMID 40426650, 2025). "Serum irisin has been found as a potential biomarker for VaD induced cognitive decline, but the state of Fndc5/irisin in VaD is not clear yet." (PMID 36823656, 2023).
Parkinson disease (7 papers, 2017 to 2026). A progressive degenerative disorder of the central nervous system characterized by loss of dopamine producing neurons in the substantia nigra and the presence of Lewy bodies in the substantia nigra and locus coeruleus. "The results demonstrated that Parkinson’s disease mice with MPTP-induced neurotoxicity had a lower relative FNDC5 protein content compared to normal mice." (PMID 41195080, 2025). "Next, we sought to clarify how FNDC5 mediates enhanced hippocampal plasticity and plays a role in the protection of cognitive function in Parkinson’s disease." (PMID 37175535, 2023).
hyperlipidemia (6 papers, 2019 to 2022). "For example, hepatocyte-specific FNDC5 knockout mice show defective autophagy, hyperlipidemia and fatty livers." (PMID 32882839, 2020). "The aim of this study was to investigate whether the nuclear receptor farnesoid X receptor (FXR) could regulate FNDC5/Irisin expression and the role of Irisin in hyperlipidemia and atherosclerosis in ApoE-/- mice." (PMID 31191305, 2019). "Noteworthy, FNDC5 overexpression prevents high-fat diet-induced hyperlipidaemia, hepatic lipid accumulation, and impaired fatty acid-b-oxidation and autophagy in liver, also ameliorating hyperlipidaemia and enhancing lipolysis in the adipose tissue of obese mice." (PMID 34206655, 2021). "CMs derived from WT and FNDC5−/− mice and H9c2 cells with FNDC5 siRNA silencing were used to determine the role of FNDC5 in hyperlipidemia-induced cardiomyocytes damage." (PMID 30940158, 2019).
Hypertension (6 papers, 2019 to 2024). The presence of chronic increased pressure in the systemic arterial system. "On the other hand, the enhanced oxidative stress and inflammasome activation in FNDC5 deficiency mice exacerbates hypertension and vascular remodeling." (PMID 32509148, 2020). "In the present study, Ang II treatment caused more severe hypertension, vascular remodeling, oxidative stress, and inflammasome activation in FNDC5 knockout mice than those in WT mice." (PMID 32509148, 2020). "It is probably that FNDC5 deficiency aggravates Ang II-induced oxidative stress and inflammasome activation, and Ang II-induced hypertension also promotes oxidative stress and inflammasome activation." (PMID 32509148, 2020). "Similar to the attenuation of irisin on Ang II-induced VSMCs remodeling, endogenous FNDC5 ablation exacerbated, and exogenous FNDC5 overexpression alleviated Ang II-induced hypertension and vascular remodeling." (PMID 38169582, 2024). "Adult male mice of wild-type, FNDC5 (irisin-precursor) knockout, and FNDC5 overexpression were used to develop hypertension by challenging them with Ang II subcutaneously in the back using a microosmotic pump for 4 weeks." (PMID 38169582, 2024). "Subcutaneous infusion of Ang II caused more serious hypertension, vascular remodeling, oxidative stress, NLRP3 inflammasome activation, AMPK phosphorylation inhibition, and SIRT1 downregulation in the aorta of FNDC5−/− mice than those of WT mice." (PMID 32509148, 2020). "Hypertension and vascular remodeling were induced by subcutaneous infusion of Ang II with a microosmotic pump for 2 weeks in wild-type mice (WT) and FNDC5 knockout mice (KO)." (PMID 32509148, 2020). "We postulated that hypertension is associated with decreased hippocampal BDNF, which can be restored by exercise‐mediated upregulation of fibronectin type‐II domain‐containing 5 (FNDC5)." (PMID 31883222, 2019). "Given that hypertension is associated with neurocognitive deficits, we examined the expression of BDNF, TrkB, FNDC5, AT1R, and MR in the CA1‐3 and DG regions of the hippocampus." (PMID 31883222, 2019). "FNDC5 in the heart and skeletal muscle appears involved in the response to hypertension, while only skeletal muscle is involved in the exercise response." (PMID 31883222, 2019). "In order to determine whether miR-31-5p is involved in the regulation of FNDC5 expression in hypertension, the effects of the miR-31-5p mimic and inhibitor on FNDC5 expression were further identified in primary VSMCs of WKY and SHR." (PMID 34440213, 2021). "The intervention of miR-31-5p or the upregulation of FNDC5 may be a potential therapeutic strategy for attenuating oxidative stress in hypertension." (PMID 34440213, 2021). "All together, these findings suggest that changes in FNDC5/BDNF signaling may play a role in cardiovascular pathologies such as hypertension or MI." (PMID 31883222, 2019). "Thus, we postulated that hypertension is associated with downregulation of BDNF‐TrkB signaling in the hippocampus, which can be rescued by exercise training through the upregulation of FNDC5 expression in skeletal muscle and brain." (PMID 31883222, 2019). "Whether FNDC5 might be involved in the beneficial effects of exercise in hypertension remains to be determined." (PMID 31883222, 2019). "Thus, targeting the skeletal muscle FNDC5/BDNF pathway through endurance exercise may benefit the heart, skeletal muscle, and brain and lead to novel therapeutic approaches against hypertension and its associated comorbidities." (PMID 31883222, 2019). "The authors of the present study aimed to investigate the role of miR-31-5p and its relation to FNDC5 in the oxidative stress and VSMC migration in hypertension." (PMID 34440213, 2021).
liver fibrosis (6 papers, 2015 to 2024). "In addition, its target mRNA Fibronectin (FNDC5 ) was down-regulated and associated with hepatic fibrosis." (PMID 25707620, 2015). "FNDC5 plays beneficial roles in attenuating liver fibrosis via AMPK phosphorylation-mediated inhibition of HSCs activation." (PMID 39359922, 2024). "It has been shown that polymorphism in the FNDC5 gene (rs3480) is associated with NAFLD progression to NASH and liver fibrosis." (PMID 36140354, 2022). "Another study showed that fibronectin type III domain-containing protein 5 (FNDC5)/irisin could attenuate liver fibrosis via inhibiting the release of HSC-derived exosomes." (PMID 39767572, 2024). "SOCS3, by virtue of its function of STAT3 signalling suppressor may also provide an anti-fibrotic contribution, as STAT3 promotes liver fibrosis, and increased gene expression of the anti-fibrotic fibronectin type III domain containing 5 (Fndc5, also known as irisin) was observed in the KD group." (PMID 35995402, 2022). "The intensity of α-smooth muscle actin (α-SMA) immunohistochemical staining in liver tissue was obviously enhanced in HFD-fed mice in both WT and Fndc5-/- mice, suggesting that HFD induced liver fibrosis in these mice." (PMID 33754067, 2021). "The α-SMA and high-mobility group box-1 (HMGB-1), another important driver of liver fibrosis 55, were significantly increased by HFD in WT and Fndc5-/- mice liver tissues." (PMID 33754067, 2021).